ITIH3 (inter-alpha-trypsin inhibitor heavy chain 3)
Diseases named in the same sentence as ITIH3 in open-access papers (continued):
Sharing a sentence is not in itself a finding about the gene and the disease.
inclusion body myositis (1 paper, 2024). A slowly progressive degenerative inflammatory disorder of skeletal muscles characterized by late onset weakness of specific muscles and distinctive histopathological features. "We have also compared our results with ITIH3 levels in IIM (12 patients with inclusion body myositis (IBM) and 2 with immune-mediated necrotizing myopathy (IMNM)) and CIDP with a similar observation." (PMID 38888758, 2024).
ischemic stroke (1 paper, 2023). A stroke disorder caused by obstruction of blood flow to the brain, due to thrombotic (local blood clot formation) or embolic (due to a blood clot or other material traveling from another site) event. "In contrast, Agt and Itih3 were significantly upregulated after ischemic stroke, implying that these genes might not perfectly represent the ETNPPL-expressing subpopulation." (PMID 36794261, 2023).
Jaundice (1 paper, 2023). Yellow pigmentation of the skin due to bilirubin, which in turn is the result of increased bilirubin concentration in the bloodstream. "Tonack and collaborators have also looked for potential plasma biomarkers for PDAC and found some candidates, but they are associated with jaundice, showing the highest sensitivity of ITIH3, C5, A1BG, PIGR, and Reg3A in this condition." (PMID 37628784, 2023).
kidney stone (1 paper, 2025). "Concurrently, six protein ratio pairs were found to inhibit kidney stone occurrence: GGT1/MME protein level ratio, ACE2/MME protein level ratio, ITIH3/VCAM1 protein level ratio, GZMA/TNFRSF8 protein level ratio, CRADD/HSPA1A protein level ratio and GZMA/TNFRSF4 protein level ratio." (PMID 40673688, 2025).
mood disorder (1 paper, 2023). A cognitive disorder a disturbance in which the person's mood is hypothesized to be the main underlying feature. "Since neuronal plasticity is thought to be altered in mood disorders and antidepressants affect astrocytes, it is possible that Itih3 in ETNPPL+ astrocytes might be involved in mood disorders or other psychiatric diseases through the regulation of neuronal plasticity." (PMID 36794261, 2023).
muscle disorder (1 paper, 2024). "Also, ITIH3 levels are not increased in IIM as a muscle disorder and CIDP as a disease of the peripheral nerves." (PMID 38888758, 2024).
myasthenia gravis (1 paper, 2024). Myasthenia gravis (MG) is a rare, clinically heterogeneous, autoimmune disorder of the neuromuscular junction characterized by fatigable weakness of voluntary muscles. "Immunostaining of muscle specimens from these patients demonstrated ITIH3 localization at the neuromuscular endplates in myasthenia gravis but not in controls, thus providing a structural equivalent for our serological findings." (PMID 38888758, 2024).
narcolepsy (1 paper, 2023). A sleep disorder characterized by a tendency for excessive sleepiness during the day which occurs even after adequate sleep in the nighttime. "Also, ITIH3 and PTPRN2 are proteins found in this study and have also been reported in proteomics profiling in narcolepsy rat models, as well as some other gene expression studies." (PMID 36979356, 2023).
pancreatic ductal adenocarcinoma (1 paper, 2026). An infiltrating adenocarcinoma that arises from the epithelial cells of the pancreas. "We evaluated a three-marker model comprising serum CA19-9 in combination with the plasma proteins ITIH3 and CEACAM1 for pancreatic ductal adenocarcinoma (PDAC) detection." (PMID 42122194, 2026).
pancreatitis (1 paper, 2025). Inflammation of the pancreas. "Additionally, our study indicates elevated ITIH3 plasma levels in patients with pancreatitis." (PMID 40885913, 2025). "The increased ITIH3 plasma levels in patients with septic shock and pancreatitis suggest that changes in ITIH3 are inflammation-dependent rather than directly driven by infection." (PMID 40885913, 2025).
Shock (1 paper, 2025). The state in which profound and widespread reduction of effective tissue perfusion leads first to reversible, and then if prolonged, to irreversible cellular injury. "Our study supports the findings regarding ITIH2 and ITIH3, but we observed a significant decrease in ITIH1 plasma levels in patients with septic shock while AMBP remained unchanged." (PMID 40885913, 2025).
thyrotoxicosis (1 paper, 2022). A hypermetabolic syndrome caused by the elevation of thyroid hormone levels in the serum. "In the present study, Itih1, Itih2, Itih3, and Itih4 were downregulated in thyrotoxicosis mice, which also reflected the decline of defense and protective capability." (PMID 35720307, 2022).
tumor (13 papers, 2008 to 2024). "In relation to expression, we observed a progressive and significant increase of ANKRD6 and ITIH3 across the tumor stages." (PMID 38480611, 2024). "These genes are ANKRD6, ITIH3, SORCS3, NPY1R and CCDC178, which form a signature associated to adverse clinic-pathological features such as advanced tumor stage, poor prognosis and disease recurrence in GC." (PMID 38480611, 2024). "According to the UALCAN website EC study cohort, tumor tissues have lower expression of ITIH3 protein (p < 0.001) and higher expression of PRXL2A protein (p < 0.001) than normal tissues." (PMID 35743699, 2022). "By conducting between-groups and paired analyses of normal and tumor tissues, the results showed that the ITIH3 mRNA level was downregulated while the other four signature genes were all upregulated in tumors." (PMID 35743699, 2022). "Inhibition of tumor growth and metastasis mediated by ITIH3 is related to its stabilizing effects on the extracellular matrix as well as covalent linkage of HA." (PMID 31481982, 2019). "Several studies have suggested that ITIH3 exerts a tumor suppressor role in disease progression." (PMID 36681849, 2023). "After validation on tumour and nontumour tissue samples, leucine-rich alpha-2-glycoprotein (LRG1) and inter-alpha-trypsin inhibitor heavy chain H13 (ITIH3) were determined as being overexpressed in tumour tissues; however, their practical use in the clinical environment is questioned." (PMID 24550697, 2014). "Noteworthy, overexpression of ANKRD6, ITIH3 and SORCS3 was detected in tumor compared with control tissue in the patients presenting poor survival." (PMID 38480611, 2024). "ITIH3, another overexpressed DEP in the PDAC-S samples, also acts in the tumor microenvironment contributing to tumor progression." (PMID 37628784, 2023). "Compared with normal tissues, tumor tissues had increased mRNA levels of GNG3 and PRXL2A and a reduced mRNA level of ITIH3." (PMID 35743699, 2022). "We also observed that the expression levels of ITIH1, ITIH3, and ITIH4 increased with tumor staging of KIRC patients, as did that of ITIH2 in KIRP patients." (PMID 33744857, 2021). "Significant alterations in Inter-alpha-trypsin inhibitor heavy chains (ITIH1, ITIH2, ITIH3, and ITIH4) levels were also observed due to their implication in tumor growth and the malignancy process." (PMID 32023884, 2020). "Our findings collectively support the utility of plasma ITIH3 and ITIH4 proteins as novel tumor biomarkers for diagnosis of CRC." (PMID 31481982, 2019). "Indeed, an in vivo experiment has already shown that the number of tumor metastases significantly decreased upon ITIH1 and ITIH3 overexpression." (PMID 33744857, 2021). "Although the expression levels of ITIH2, ITIH3, and ITIH4 also differed in different tumor stages of LIHC, the expression change directions were not always identical." (PMID 33744857, 2021).
cancer (12 papers, 2008 to 2025). A tumor composed of atypical neoplastic, often pleomorphic cells that invade other tissues. "Downregulation of ITIH3 expression was seen in cancers of the breast (51%), uterus (62%), colon (67%), ovary (71%), lung (86%), rectum (72%), and prostate (4 out of 4 samples)." (PMID 18226209, 2008). "Interestingly, previous reports suggest blood ITIH3 to be elevated for a similar range of cancers as C9, namely, lung, gastric, pancreatic and colorectal cancers." (PMID 37147936, 2023).
infection (6 papers, 2015 to 2025). The state of being infected such as from the introduction of a foreign agent such as serum, vaccine, antigenic substance or organism. "Bone marrow proteoglycan 2 (Prg2), inter-alpha-trypsin inhibitor heavy chain H3 (Itih3), and three fibrinogen proteins (Fga, Fgb, Fgg) showed similar patterns of abundance with elevated levels during infection over time." (PMID 41061967, 2025). "Of the top 20 contributing proteins for each infection identified by machine learning, 6 were found to be common to both LD and WNV (APOD, C4BPB, C7, HP, ITIH3, PGLYRP2), but with varying degrees of importance in each disease." (PMID 36569838, 2022). "In this study, ITIH1, ITIH2, were found to be negative acute phase reactants while ITIH3, and ITIH4 acted as positive acute phase proteins during both infection types in NHPs." (PMID 30774579, 2019).
psychiatric disorder (4 papers, 2020 to 2025). A disorder characterized by behavioral and/or psychological abnormalities, often accompanied by physical symptoms. "Therefore, ITIH3 is intricately involved in the potential occurrence of various psychiatric disorders." (PMID 38637810, 2024).
bacterial infection (1 paper, 2025). "Patients with bacterial infection had lower plasma levels of AMBP and ITIH2, an increase in ITIH3, while ITIH1 remained unchanged compared with healthy controls." (PMID 40885913, 2025).
cardiovascular disease (1 paper, 2025). "Further studies are required to elucidate the pathophysiological roles of ITIH3 in cardiovascular disease and to support its potential use as a biomarker." (PMID 40908499, 2025).
neurodevelopmental disorder (1 paper, 2020). A behavioral and cognitive disorder with onset during the developmental period that involves impaired or aberrant development of intellectual, motor, or social functions. "ITIH3 showed genome-wide significant association with neurodevelopmental disorders in European populations." (PMID 32251353, 2020).
ITIH3 also shares sentences with these, for which no sentence is quoted: autism spectrum disorder (2 papers); colon adenocarcinoma (2); Hypertension (2); lung adenocarcinoma (2); lung diseases (2); prostate carcinoma (2); alcohol use disorders (1); bladder cancer (1); bladder urothelial carcinoma (1); cervical squamous cell carcinoma (1); clear cell renal cell carcinoma (1); cocaine use disorder (1); colon carcinoma (1); cystitis (1); digestive system cancer (1); endometrial cancer (1); gout (1); Hepatic steatosis (1); liver cancer (1); lung squamous cell carcinoma (1); mesothelioma (1); metabolic disorders (1); metastatic disease (1); neurogenic muscular atrophy (1); ovarian serous cystadenocarcinoma (1); polymyalgia rheumatica (1); pulmonary arterial hypertension (1); rectum cancers (1); renal cell carcinoma (1); rheumatoid arthritis (1).
A further 4 diseases each share a sentence with ITIH3 in 1 paper.